TPMT (thiopurine S-methyltransferase)
Diseases named in the same sentence as TPMT in open-access papers (continued):
Sharing a sentence is not in itself a finding about the gene and the disease.
Down syndrome (1 paper, 2015). "None of the TPMT*1/*3C children had CNS disease at diagnosis or Down syndrome, two had T‐cell immunophenotype and one of these relapsed." (PMID 25441457, 2015).
hepatoma (1 paper, 2015). "The three hepatoma cell lines tested had identical TPMT genotypes, but a variance in TPMT activity was noticed." (PMID 25916701, 2015).
Hypoglycemia (1 paper, 2019). A decreased concentration of glucose in the blood. "Our data shows that the same mechanism of allopurinol to inhibit TPMT to treat hepatotoxicity in IBD can be applied to reverse symptoms of hypoglycemia by lowering 6MMP levels." (PMID 30828444, 2019).
liver failure (1 paper, 2022). A liver disease characterized by the liver losing or has lost all of its function. "Furthermore, an initial screening for TPMT and NUDT15 can predict the drug response in advance, give an appropriate initial dose, and be used for post-mortem detection of severe myelotoxicity, liver failure, and drug resistance to find the genetic causes of ADR and drug resistance." (PMID 35935867, 2022).
macrocytic anemia (1 paper, 2018). Anemia that is characterized by increased red blood cell volume. "TPMT genotype was not related to occurrence of macrocytic anemia, liver toxicity, infection, or intolerance to azathioprine." (PMID 29630648, 2018).
neuropathy (1 paper, 2012). A disorder affecting the nervous system that manifests with pain, tingling, numbness, and/or muscle weakness. "We found statistically significant associations of four SNP markers (rs4646316, rs4380755, rs5008499, and rs6591256) in or near COMT, TPMT, and GSTP1 with neuropathy and five SNP markers (rs3788306, rs12189790, rs17420046, rs6938294, and rs6912842) with ototoxicity at the nominal p-value of 0.05." (PMID 23248619, 2012).
non-Hodgkin lymphoma (1 paper, 2023). Distinct from Hodgkin lymphoma both morphologically and biologically, non-Hodgkin lymphoma (NHL) is characterized by the absence of Reed-Sternberg cells, can occur at any age, and usually presents as a localized or generalized lymphadenopathy associated with fever and weight loss. "Dosage is dependent on the patient’s levels of enzyme serum thiopurine S-methyltransferase (TPMT); when TPMT is low, the risk of myelosuppression, non-melanoma skin cancer, and non-Hodgkin’s lymphoma is enhanced." (PMID 38002251, 2023).
pemphigus vulgaris (1 paper, 2020). Pemphigus is a group of chronic autoimmune skin diseases characterized by blister formations on the outer layer of the skin and the mucous membranes. "In our research we evaluated an ELISA based phenotype assay for TPMT in our pemphigus vulgaris patients and we demonstrated that two patients showed decreased level of TPMT antigen, but the patient showed normal lab data despite receiving standard doses of AZA." (PMID 32944042, 2020).
primary biliary cirrhosis (1 paper, 2021). "Ailing reported the first case of a 40-year-old Chinese primary biliary cirrhosis and autoimmune hepatitis overlap syndrome with AZA-induced severe toxicity with no clinically significant TPMT variant but with the NUDT15 c." (PMID 33950972, 2021).
renal failure (1 paper, 2020). "Some factors affecting the TPMT activity includes gender (higher in males), comorbid conditions (renal failure) and co-administration of certain medications." (PMID 32944042, 2020).
Sepsis (1 paper, 2016). Sepsis is defined as life-threatening organ dysfunction caused by a dysregulated host response to infection. "The TPMT genotype was also identified as the strongest single genetic predictor for sepsis/recurrent infections (by all methods), for stomatitis (by LR and CART methods) and was associated with the occurrence of dose reductions due to therapy toxicities." (PMID 27452984, 2016). "Further genotype information did not improve the predictive model for the occurrence of sepsis/recurrent infections, with age at diagnosis and TPMT genotype remaining the only statistically significant predictors for recurrent infections after Bonferroni correction (p = 0.00015)." (PMID 27452984, 2016).
Stevens-Johnson syndrome (1 paper, 2014). Stevens-Johnson syndrome is a limited form of toxic epidermal necrolysis characterized by destruction and detachment of the skin epithelium and mucous membranes involving less than 10% of the body surface area. "So far, 515 patients have been genotyped for HLA-B*1502 which is associated with risk of developing Stevens-Johnson syndrome following use of carbamazepine, in addition to 318 patients genotyped for TPMT in patients that may be treated with thiopurines." (PMID 24723935, 2014).
stomatitis (1 paper, 2016). Inflammation of the oral mucosa due to local or systemic factors. "In the logistic regression analysis, the addition of the MTRR genotype variable to the predictive model for stomatitis already including TPMT genotype improved the model, although the effect of this addition was not statistically significant." (PMID 27452984, 2016). "A new genetic classifier, composed of MTRR rs1801394 and MTHFR rs1801133, was the best predictor of stomatitis and was proved to be statistically significant in the subsequent LR analysis, adjusted to treatment protocol, age at diagnosis, gender and TPMT genotype." (PMID 27452984, 2016).
thrombophilia (1 paper, 2025). A condition characterized by an abnormally high level of thrombi. "In contrast, testing for TPMT and factor V Leiden is more frequently requested due to well-established clinical indications, such as thiopurine therapy and thrombophilia screening." (PMID 40573293, 2025).
cancer (29 papers, 2012 to 2025). A tumor composed of atypical neoplastic, often pleomorphic cells that invade other tissues. "In this regard, the AmpliSeqTM for Illumina® Childhood Cancer Panel only allowed the identification of TPMT variants." (PMID 35463953, 2022). "A retrospective study showed reducing 6-MP starting dose based on TPMT polymorphisms reduced second malignant neoplasm (SMN) risk but increased relapse risk." (PMID 34660484, 2021). "CBC-D weekly×1 month, q2 weeks×2 months→monthly.ALT, AST, GGT, ALP, bilirubin, albumin, INR q3months.Age-related cancer screening and skin checks.Consider testing for thiopurine S-methyltransferase (TMPT) deficiency before initiation." (PMID 34108243, 2021). "Jude Children’s Hospital protocols, low TPMT activity is associated with higher risk ofsecondary cancers, in contrast to patients treated with the BFM protocols where no such association was found." (PMID 24734162, 2014). "A subsequent NOPHO trial (NOPHO ALL‐2000) reported that using reduced mercaptopurine dosages for the TPMT heterozygote patient, alongside high‐dose methotrexate, reduced the risk of developing second cancers but this was counterbalanced by an increased risk of relapse for the TPMT heterozygote." (PMID 25441457, 2015). "For example, polymorphisms in the thiopurine methyltransferase (TPMT) gene have been linked to susceptibility to thiopurine-induced marrow suppression in patients, and preemptive TPMT genotype-guided dosing represents a successful example of genetics-based precision medicine in cancer treatment." (PMID 32873882, 2020). "Further markers include thiopurine S-methyltransferase (TPMT) and catechol O-methyltransferase (COMT) variants associated with cisplatin-related hearing damage in frontline paediatric cancer treatment." (PMID 34192550, 2021). "However, pharmacogenetic testing for the TPMT alleles *2 (rs1800462), *3A (rs1800460 and rs1142345), *3B (rs1800460) or *3C (rs1142345) is recommended by the Canadian Pharmacogenomics Network for Drug Safety in pediatric cancer patients when prescribing cisplatin (PharmGKB ID PA166170751)." (PMID 32629971, 2020). "TGNs integrate within DNA and RNA leading to cancer cell death, what is inactivated by cytosolic Thiopurine S-methyltransferase (TPMT) enzyme via S-methylation." (PMID 35582138, 2019). "We propose that this cancer selectivity is due to differences in thiopurine methyltransferase (TPMT) expression between normal and cancer cells." (PMID 30055072, 2018). "Further molecular and functional studies carried out in vitro on several cancer cell lines have demonstrated that SAM is responsible for direct post-translational TPMT stabilization, resulting in increased TPMT activity." (PMID 25303517, 2014). "TPMT activity is an important measure in pediatric cancer because it can affect how a patient metabolizes 6MP, which could potentially influence the metabolite profile group membership for that patient." (PMID 32192028, 2020). "In our study, we found TPMT expression to be lower in cancer cells than in normal HPDE cells." (PMID 30055072, 2018). "To test this hypothesis, we evaluated a selected panel of SNPs in GSTP1, COMT, and TPMT with cancer outcome, ototoxicity, and peripheral neuropathy in an existing cohort of men with TGCT who have received at least one course of cisplatin-based chemotherapy." (PMID 23248619, 2012).
cancer (continued). "Interestingly, both the phase II genes (UGT1A1 and TPMT) predominantly affect drugs for cancer." (PMID 38535119, 2024). "Variants of thiopurine S-methyltransferase TPMT (rs12201199, rs180046 and rs1142345) and catechol O-methyltransferase (COMT) (rs4646316 and rs9332377) were reported to be associated with ototoxicity after treatment with cisplatin in different cancers, including HGOS." (PMID 32629971, 2020). "The BFM studies report that TPMT status is not a risk factor for the development of second cancers." (PMID 25441457, 2015). "Thiopurine Methyltransferase (TPMT) is crucial in metabolizing thiopurine drugs, such as azathioprine and mercaptopurine, used in cancer treatment and autoimmune disorders." (PMID 40430848, 2025). "Based on the result showing antitumor effect of 6‐TG in TPMT‐low PDAC, we then analyzed TCGA data to estimate the expression level of TPMT in PDAC compared with various types of cancer." (PMID 30055072, 2018). "Among the FDA-approved biomarkers for anti-cancer drugs, there are: cytochrome P450 2D6 (CYP2D6) for tamoxifen; rucaparib and dihydropyrimidine dehydrogenase (DPYD/DPD) for fluorouracil and capecitabine; and thiopurine S-methyltransferase (TPMT) for cisplatin, mercaptopurine, and thioguanine." (PMID 35205356, 2022).
tumor (4 papers, 2014 to 2022). "AZA-induced myelosuppression and skin reactions were related to thiopurine S-methyltransferase (TPMT) polymorphisms." (PMID 25101277, 2014).
infection (2 papers, 2018 to 2025). The state of being infected such as from the introduction of a foreign agent such as serum, vaccine, antigenic substance or organism. "Its use is complicated by variable metabolism (requiring TPMT genotyping) and risks such as myelosuppression, gastrointestinal toxicity, and infection susceptibility." (PMID 40981278, 2025).
hematologic malignancy (1 paper, 2021). "This study reports the frequency of TPMT*3C in Thai children without hematologic malignancy compared to Thai children with ALL at 2.5 and 5.7%, respectively." (PMID 34442427, 2021).
metabolic disorders (1 paper, 2023). "If clinical symptoms are appropriate, drug-metabolizing enzymes may be determined to detect metabolic disorders associated with hypersensitivity to certain drugs (e.g., thiopurine S-methyltransferase (azathioprine)) (consensus)." (PMID 37705676, 2023).
peripheral neuropathy (1 paper, 2012). A disorder affecting the peripheral nervous system. "A total of 90 markers in GSTP1, COMT, and TPMT and their adjacent genomic regions (±20 kb) were analyzed for associations with refractory TGCT after first course of chemotherapy, progression-free survival (PFS), overall survival (OS), peripheral neuropathy, and ototoxicity." (PMID 23248619, 2012). "This study examined the association between three genes involved in cisplatin metabolism, GSTP1, COMT, and TPMT, with TGCT outcomes and cisplatin-induced ototoxicity and peripheral neuropathy." (PMID 23248619, 2012). "Although one SNP of TPMT in our study (rs11964408) was in linkage disequilibrium with rs12201199, its relatively weak linkage with rs12201199, with a correlation coefficient of 0.65, may explain the lack of significant association with peripheral neuropathy." (PMID 23248619, 2012).
TPMT also shares sentences with these, for which no sentence is quoted: ulcerative colitis (5 papers); rheumatoid arthritis (4); alopecia (2); colorectal cancer (2); Pneumocystis carinii pneumonia (2); Prediabetes (2); tuberculosis (2); acquired aplastic anemia (1); allergic reactions (1); angioedema (1); antineutrophil cytoplasmic antibody associated vasculitis (1); aplastic anemia (1); appendicitis (1); Arthralgia (1); atopic dermatitis (1); autoimmune disorders (1); blood cancer (1); brain tumours (1); breast carcinoma (1); chronic kidney disease (1); colon cancer (1); diffuse large B-cell lymphoma (1); eosinophilia (1); erythema multiforme (1); Fulminant hepatitis (1); G6PD deficiency (1); Guillain-Barre syndrome (1); head and neck squamous cell carcinoma (1); hearing disorder (1); Hearing impairment (1).
A further 23 diseases each share a sentence with TPMT in 1 paper.